IL10 (interleukin 10)
Diseases named in the same sentence as IL10 in open-access papers (continued):
Sharing a sentence is not in itself a finding about the gene and the disease.
parasitemia (continued). "Our findings identify Blimp-1-dependent IL-10 produced by Tr1 cells as a critical regulator of IFNγ-dependent, TNF-mediated tissue damage in the spleen in parasitic infections." (PMID 26765224, 2016). "We observed the children after 1 month and 3 months and analyzed their blood samples for parasitemia, lymphocyte subsets, and levels of the cytokines interferon (IFN)-γ, IL-10, and transforming growth factor (TGF)-β." (PMID 26335932, 2015). "Tregs, which over-express a subset of regulatory cytokine genes including those coding for IL-10 and TGF-β, play an important role in promoting immune tolerance in a number of parasitic disease models." (PMID 25955764, 2015). "Treg cells inhibit the immune response of effector T cells by secreting large amounts of IL-10 and TGF-β, which play critical roles of immune evasion in human parasitic infection." (PMID 24799769, 2014). "Consistent with other studies on parasitic infection, we found that CD4+T cells produce higher levels of IFN-γ and IL-10 after CD25+cell depletion following pVAX1-Sj26GST immunization." (PMID 22802961, 2012). "The remarkable elevation in the expression levels of IL-10 and TGF-β genes in rats treated with salvia fraction may have a role in reducing parasitemia." (PMID 40571943, 2025). "Parasitemia was determined by the Brener method and relative gene expression (RGE) of six cytokines was evaluated by RT-qPCR to determine the Th1 response (IFN-γ, TNF-α, IL-1β, IL-12) and the Th2 response (IL-4 and IL-10)." (PMID 40743218, 2025). "This pattern is consistent with observations in other parasitic diseases, where IL-10 functions to maintain immune homeostasis rather than serve as a reliable marker of active infection." (PMID 40526709, 2025). "The results show that IL10 blockade did impact some aspects of the immune response including B cell, T cell and macrophage responses, but this was not sufficient to normalize parasitemia." (PMID 41191641, 2025). "In the present study, the expression of cytokines such as IFN-γ, IL-10, IL-12, CYP-1α, and IL-1β significantly increased in fish infected with Clinostomum and Euclinostomum, suggesting an immune response aimed at combating the parasitic infection." (PMID 41152306, 2025). "Among the promising findings, Pereira-Chiocolla and colleagues demonstrated the protective potential of immunizing mice with T. gondii-derived EVs, resulting in increased specific antibodies, elevated IFN-γ, IL-10, TNF-α, and IL-17 expression, reduced parasitemia, and higher survival rates." (PMID 40141288, 2025). "Moreover, our current results are in line with existing literature that has documented associations between pro-inflammatory cytokines such as IL-6, IL-10 and IFN-γ and parasitemia." (PMID 39407132, 2024). "On the contrary, upon infection with PbNK65-NY and P. yoelii, a decrease in parasitemia in the absence of IL-10 was found, suggesting that IL-10 impairs the protective anti-parasitic immune response." (PMID 39355242, 2024). "However, correlation studies were conducted between parasitemia and IFN-γ, IL10, and NO levels, revealing a positive correlation between IFN-γ and eleutherin, where no antiparasitic effect was observed." (PMID 39703398, 2024). "The meta-regression analysis using the study designs, geographic location (continents), Plasmodium spp., age, mean parasitemia, and methods for the IL-10’s quantification showed that these covariates did not confound the pooled SMD (p > 0.05)." (PMID 36668942, 2023). "In T. cruzi-infected nonpregnant women, IL-12p70 IL-15, IFN-γ, and TNF-α levels were positively correlated with parasitemia, whereas IL-10 was not." (PMID 38133693, 2023). "The deviation is exacerbated by the three mice that succumbed to parasitemia during the first peak and did not have the opportunity for Th2 type responses, mediated by IL10, IL13, IL4, and IL6 to develop." (PMID 35634275, 2022).
parasitemia (continued). "When IL-10 is blocked during the first 4 days of infection, mice have increased parasitemia and succumb to infection, while no such phenotypes are observed if IL-10 is blocked after day 4 p.i.." (PMID 35631044, 2022). "The population of IL-10 producing B220+CD5+CD1d+ cells was found to be directly correlated with the increase of parasitemia in both lethal and non-lethal strains of Plasmodium at early stage of infection." (PMID 35625397, 2022). "IL-10 median levels were always lower in the case of STH regardless of age, whereas the level of IL-6 was reduced in individuals infected with filariae and intestinal parasitosis." (PMID 35421083, 2022). "We also observed a negative correlation between TLR4, TLR5, TRIF, IL-6, IL-10, and IL-12p35 mRNA expression and parasitemia peak levels in infected mice." (PMID 34336720, 2021). "On the other hand, the regulatory cytokine IL-10 exerts control of the leukocyte activation/chemoattracting by inhibition of the NF-kB and ERK/MAPK, which minimize the cardiomyocytes damage induced by the parasite infection." (PMID 34722326, 2021). "We did not observe NK cells producing IL-10 during the chronic stage of parasite infection and they also did not increase their expression of PDL1, the ligand for PD1." (PMID 32733814, 2020). "The anti-MIF Nb treatment did not affect parasitemia development in TgAlbCre-IL10-/- mice, but it clearly prevented anemia from further progressing." (PMID 32012211, 2020). "FoxP3+ regulatory T cells (Tregs) produce TGF-beta and IL-10 but their role in this parasitic disease is still not clear." (PMID 32517744, 2020). "We show here, that Plasmodium yoelii 17XNL (Py) infected mice had impaired clearance of systemic Listeria monocytogenes (Lm) during both acute parasitemia and up to 2 months after clearance of Py infected red blood cells that was independent of HO-I and IL-10." (PMID 32714882, 2020). "T cell-specific inactivation of IL-10 had also no impact on parasitemia in P. yoelii-infected BALB/c mice in our hands and on parasite burden in C57BL/6 mice infected with P. chabaudi." (PMID 28293237, 2017). "Consistent with the plasma IL-10 data, significantly increased frequencies and numbers of total IL-10–GFP+ cells were observed in the spleen and liver during the period of patent parasitemia on day 2 and/or day 4 after secondary-infected mice compared with primary-infected mice." (PMID 27630165, 2016). "Using the Trypanosoma brucei brucei GVR35 experimental infection model, we demonstrate that systemic delivery of the counter-inflammatory cytokine IL-10 lowers plasma IFN-γ and TNF-α concentrations, CNS parasitosis and ameliorates neuro-inflammatory pathology and clinical symptoms of disease." (PMID 26505761, 2015). "Similar results were observed for total IL-10 and total IFNγ-producing populations, and when assessing the duration since last episode of parasitemia (data not shown)." (PMID 24415936, 2014). "Pressurized oxygen therapy reduced peripheral parasitemia, expression of TNF-α, IFN-γ and IL-10 mRNA levels and percentage of γδ and αβ CD4+ and CD8+ T lymphocytes sequestered in mice brains, thus resulting in a reduction of blood-brain barrier (BBB) dysfunction and hypothermia." (PMID 18769544, 2008). "However, anti-IL10 treatment did not significantly alter markers of macrophage activation or parasitemia, indicating that blockade of a single factor produced by expanded Bregs is not sufficient to fully restore immune defence." (PMID 41191641, 2025). "However, the mixed generation of anti-inflammatory (IL-10) and pro-inflammatory (IL-18) immune mediators can negatively interfere with the activation of the cellular immune response, favoring parasite infection." (PMID 38474410, 2024).
parasitemia (continued). "However, the interesting results were the significant higher concentrations of pro-inflammatory TNF-α- and lower concentrations of anti-inflammatory IL-10- cytokine in the RAP children without organic disease compared to children with parasitic infections." (PMID 34539633, 2021). "Thus, CD4+IL-10+ and CD4−CD8−L-10+ T cells play essential roles in immunoregulation of parasitic infections, which may be one mechanism of immune evasion by C. cellulosae." (PMID 34540719, 2021). "It has been reported that NF-B are significant IL-10 producers in healthy individuals and expand in several viral (HIV, HCV) and bacterial infections, thus, they might represent a new regulating subset in parasitic infections, as Chagas disease." (PMID 35071041, 2021). "Likewise, IL-10 can inhibit the production of TNF-α and counteract detrimental biological effects on the overall state of the animal once the maximum peak of parasitemia has been surpassed, as reflected in the healthy appearance of C-TIM after parasitemia." (PMID 35059328, 2021). "Besides clearing parasitemia, this treatment also resulted in a lower pulmonary mRNA expression of the inflammatory chemokines CCL2 and CXCL10, and of the cytokines tumor necrosis factor-α (TNF-α), IFN-γ, and IL-10." (PMID 33664739, 2020). "Thus, balance between these 3 cytokines; IFN-γ, TNF-α, and IL-10 levels are critical for moderating parasitic disease severity, and establishment of long-term, non-fatal diseases." (PMID 30619263, 2018). "Furthermore, we analyzed the ability of the draining lymph node cells from SGE-1X-, SGE-3X- or PBS-inoculated mice at the 7th week post-infection to produce IL-10 and IFN-γ in an attempt to understand the mechanism by which saliva exacerbates or protect mice against parasitic infection." (PMID 23656976, 2013). "Similar significant correlations were also observed between parasitemia and absolute numbers of Treg expressing GITR (Rs = 0.66, P = 0.0017), CTLA-4 (Rs = 0.47, P = 0.0349), IFN-γ (Rs = 0.52, P = 0.0187), TGF-β (Rs = 0.66, P = 0.0016), IL-10 (Rs = 0.59, P = 0.0067) and IL-17 (Rs = 0.68, P = 0.0011)." (PMID 20224778, 2010). "Neutrophils may be also implicated in immunoregulation as a source of cytokines, such as interleukin-2 (IL-12), interleukin-10 (IL-10), gamma interferon (IFN-γ) and TNF-α, thus establishing a link between innate and adaptative immunity during parasitic infection." (PMID 21082032, 2010). "Among the 80% of children who had a parasite infection in the preceding 3 months (with or without symptoms), there was a highly significant positive correlation between the frequencies of Pf-specific total IL10 producing CD4 T cells and parasite density during infection (rho = 0.35, p < 0.0001)." (PMID 29097996, 2017). "However, lower levels of a few key cytokines, such as TNF-α and IL-10, may be the key to controlling parasitemia without exacerbating anemia." (PMID 27418744, 2016). "Thus, while reduction of parasitemia may have contributed to the improved control of S. Typhimurium after IL-10 blockade, it may not be sufficient on its own to restore immune responses during the acute phase of infection." (PMID 26366739, 2015). "In certain viral or parasitic infections, high amounts of stimulation may lead to the chronic nonhealing infection shown to be regulated by IL-10." (PMID 19646904, 2009). "Several recent findings have shown that CD8+ T cells are capable of secreting IL-10 with or without CD4+ T-cell help and are involved in the regulation of immune response during virus or parasite infection." (PMID 36046744, 2022). "Accordingly, depletion of either CD4+ or CD8+ T cells resulted in a significant decrease in IL-10 levels in the lung and full protection from MA-ARDS, without affecting parasitemia." (PMID 35768411, 2022).
parasitemia (continued). "Together, our findings provide new information on the roles of galectin-1 during parasitic infection and indicate an important role for this molecule in tissue-specific Th1 cell development, but not CD4+ T cell IL-10 production." (PMID 29075269, 2017). "Interestingly, our data show that parasite infection in the presence of nucleosides did not alter IDO and TGF-β levels but induced expression of IL-10 and COX2 mRNA both in vitro and in vivo." (PMID 25849562, 2015).
periodontitis (257 papers, 2010 to 2026). An acute or chronic inflammatory process that affects the tissues that surround and support the teeth. "In contrast, those with stable periodontitis and the control group had similar IL-10 levels, suggesting that the exacerbation of periodontitis is associated with reduced IL-10 levels." (PMID 41289041, 2025). "The excessive effect of IL10 on periodontitis recovery is possibly implicated with down‐regulation of proinflammatory cytokines and matrix metalloproteinases (MMPs) as well as osteoblastic activation." (PMID 41181974, 2025). "Injection of neutralizing IL-17 antibodies in IL-10-/- mice reduced alveolar bone loss (ABL) due to experimental periodontitis." (PMID 41289041, 2025). "Polymorphisms such as IL10 −1082 A>G have been associated with altered IL10 expression and an increased risk of chronic periodontitis." (PMID 41300760, 2025). "Genetic polymorphisms in the IL10 gene have been linked to susceptibility to periodontitis, underscoring its central role in modulating disease risk and progression." (PMID 41155385, 2025). "In the Iranian population, IL-10–592 C/A, IL-10–819 C/T genes were significantly associated with periodontitis." (PMID 41289041, 2025). "It explores the involvement of HPA axis effectors—cortisol and IL-10—in modulating the inflammatory milieu associated with periodontitis." (PMID 41289041, 2025). "The −1082A > G(rs1800896) polymorphism affects IL-10 transcriptional activity, with the G allele linked to higher IL-10 production and associated with a decreased risk of chronic periodontitis in Caucasians and Latinos." (PMID 41289041, 2025). "Surprisingly, higher baseline IL-10 levels in GCF have been linked to improved clinical outcomes following treatment in patients with aggressive periodontitis." (PMID 41289041, 2025). "Studies have shown that individuals with low IL-10-producing genotypes, specifically those with IL-10 polymorphisms, are more susceptible to severe periodontitis due to a heightened inflammatory response." (PMID 41289041, 2025). "ROC curve analysis revealed that combinations of CTRP-1, TNF-α, and IL-10 exhibited excellent diagnostic accuracy in differentiating periodontitis and gingivitis from a healthy condition." (PMID 40542868, 2025). "Stimulation with P. gingivalis LPS (a TLR4 agonist) and CpG increases the percentages of IL-10-expressing CD1dhi CD5+ B cells in P. gingivalis-associated ligature-induced experimental periodontitis." (PMID 41289041, 2025). "IL-1β and IL-10 have great diagnostic capabilities when used separately or in combination for the diagnosis of periodontitis." (PMID 39445112, 2024). "Despite the limitations of this study, salivary IL-1β and IL-10 potentially possess a high diagnostic power for discriminating periodontal health from periodontitis as well as for distinguishing stable from unstable periodontitis." (PMID 39445112, 2024). "The important role of IL-10 was underscored by studies in genetically engineered mice showing that IL-10-deficient mice exhibit a hyperinflammatory phenotype and are highly susceptible to Porphyromonas gingivalis-induced periodontitis." (PMID 39253090, 2024). "Our findings revealed a significant association between specific IL-10 SNPs alleles and the severity of periodontitis, underscoring the role of genetic factors in the pathogenesis of this condition." (PMID 39336814, 2024). "Preliminary studies examining DC‐derived EVs in an experimental periodontitis model have shown the ability of DC EVs enriched with TGF β/IL‐10 to reduce alveolar bone loss." (PMID 38758729, 2024). "The objective of the recent study is to investigate the impact of IL-10 single-nucleotide polymorphisms (SNPs) on the severity of periodontitis in a cohort of Bulgarian patients." (PMID 39336814, 2024). "For instance, the IL10–1082 polymorphism and the IL-10 -592C>A polymorphism were identified as a putative risk factors for chronic periodontitis." (PMID 39253090, 2024).
periodontitis (continued). "IL-1β, IL-10, and IL-1β/IL-10 had significant diagnostic accuracy for differentiating healthy control from unstable periodontitis (AUCs = 0.99, 0.96, and 1; sensitivity = 0.98,1, and 1; specificity = 0.95, 0.95, and 1, respectively)." (PMID 39445112, 2024). "Significant associations were observed between the periodontitis and IL-10 and IL-18 levels (OR = 1.46, %95 CI 1.19–1.795; OR = 1.13, %95 CI 1.059–1.207, respectively) (p < 0.001, p < 0.001, respectively)." (PMID 39080003, 2024). "Previous research has demonstrated that single nucleotide polymorphisms in the interleukin 1 gene, interleukin 10 gene, Fc gamma gene, and tumor necrosis factor-alpha gene are related to periodontitis in terms of genomic indicators of the disease." (PMID 38337597, 2024). "Firstly, studies in experimental models of periodontitis showed that suppression of pro-inflammatory cytokines such as IL-17A or activation of anti-inflammatory cytokines such as IL-10 can ameliorate inflammation and bone loss." (PMID 39253090, 2024). "In this study, we examined the impact of IL-10 single-nucleotide polymorphisms (SNPs) on the severity of periodontitis within a cohort of Bulgarian patients." (PMID 39336814, 2024). "This is supported by research investigating the correlation between IL-10 polymorphisms and periodontal disease in patients with severe periodontitis compared to healthy individuals/control group." (PMID 39336814, 2024). "According to the existing literature, IL-10 is significantly associated with the risk of developing periodontitis." (PMID 39336814, 2024). "This importance was highlighted in experiments using IL-10-deficient mice, which demonstrated a marked susceptibility to periodontitis induced by Porphyromonas gingivalis and exhibited pronounced pro-inflammatory phenotypes." (PMID 39336814, 2024). "This broad spectrum of associations highlights the complex role of IL-10 in immune regulation and disease susceptibility, underlining the need for further research to clarify its precise role in periodontitis." (PMID 39336814, 2024). "In patients with periodontitis, IL-10 gene polymorphisms have been identified, underlining the potential relevance of IL-10 in this disease." (PMID 39253090, 2024). "This statement is supported by studies comparing patients with severe periodontitis to healthy controls, which examine the association between IL-10 polymorphisms and periodontal disease." (PMID 39336814, 2024). "According to some authors, a decline in pro-inflammatory cytokines and an increase in IL10 level were linked to improved clinical parameters in periodontitis." (PMID 37570272, 2023). "Another study showed that IL-10-1082 SNP was associated with chronic periodontitis and the IL-10-1082G allele increased the susceptibility to chronic periodontitis in Iranians." (PMID 35454140, 2022). "IL-10, an anti-inflammatory factor, was revealed to dampen IL-17-mediated periodontitis-associated inflammatory network." (PMID 35464198, 2022). "The IL-10 SNP (− 1081) was assessed in two studies, and it was only associated to PI in German smoker patients or with a history of periodontitis." (PMID 35061134, 2022). "The current meta-analysis showed that the IL-10 −592C > A polymorphism was statistically associated with periodontitis risk in the overall population." (PMID 35454140, 2022). "Other clinical and animal studies reported enhanced serum levels for IFN-γ, TNF-α, and IL-10, as well as decreased IL-2 levels in patients with A. actinomycetemcomitans- and P. gingivalis-associated periodontitis." (PMID 35203495, 2022). "An unbalanced oral microbiome causes periodontitis and systemic disease by activating proinflammatory cytokines (IL‐1, IL‐7, IL‐10, IL‐17, IL‐8, TNF‐α, and MCP‐1) and neutrophils." (PMID 35578891, 2022). "A previous study showed that IL-10 knockout mice are highly susceptible to P. gingivalis-induced periodontitis." (PMID 36050950, 2022).